AURKA (aurora kinase A)
Diseases named in the same sentence as AURKA in open-access papers (continued):
Sharing a sentence is not in itself a finding about the gene and the disease.
embryonal carcinoma (1 paper, 2010). A non-seminomatous malignant germ cell tumor characterized by the presence of large germ cells with abundant cytoplasm resembling epithelial cells, geographic necrosis, high mitotic activity, and pseudoglandular and pseudopapillary structures formation. "The level of AURKA was highest in embryonal carcinomas (16%), whereas teratomas showed the same level as normal testis (5%)." (PMID 20411023, 2010).
esophageal tumor (1 paper, 2022). "In the present study, we found that oxethazaine, a local anesthetic, was a novel AURKA inhibitor and suppressed the proliferation and migration ability of ESCC cells in vitro and patient-derived esophageal tumor growth and tumor metastasis in vivo." (PMID 35217647, 2022).
experimental autoimmune encephalomyelitis (1 paper, 2019). An autoimmune demyelinating disease of the central nervous system that is produced experimentally in animals by the injection of homogenized brain or spinal cord in Freund's adjuvant. "AURKA has been found to play a role in experimental autoimmune encephalomyelitis (EAE) by regulating M1 macrophage polarization." (PMID 31494269, 2019).
fibrolamellar carcinomas (1 paper, 2023). "This c-Myc overexpression resulted from Aurora kinase A overexpression derived from the activity of a chimeric kinase that is the final transcript of a deletion in chromosome 19, common to all fibrolamellar carcinomas." (PMID 36788919, 2023). "Fibrolamellar carcinoma and adenomyomatosis samples presented increased expression of Aurora kinase A, c-MYC, and ornithine decarboxylase when compared to normal liver, while ornithine transcarbamylase was decreased." (PMID 36788919, 2023).
fibrosis (1 paper, 2025). the formation of excess fibrous connective tissue in an organ or tissue in a reparative or reactive process. "Experimental validation in a bleomycin-induced fibrosis model confirmed the upregulation of GRGs (such as AURKA, CXCR4)." (PMID 40093327, 2025).
Gliosis (1 paper, 2023). Gliosis is the focal proliferation of glial cells in the central nervous system. "H3K27M DMG patient tumor samples demonstrated high AURKA protein levels while tissue samples from gliosis patients did not have any AURKA expression." (PMID 37128506, 2023).
hemangioblastoma (1 paper, 2019). "Surface B is also phosphorylated by AURKA and CSNK1A1 at Ser72, and patients with mutations affecting this residue develop hemangioblastomas and RCC." (PMID 30943211, 2019).
HIV-1 infection (1 paper, 2023). The type species of lentivirus and the etiologic agent of acquired immunodeficiency syndrome (AIDS). "Thus, while HIV-1 infection increases AURKA and AURKB levels in newly infected cells, later cell-cell interactions and Env signaling appear to function to counter undesirable AURKB activity at the plasma membrane that would otherwise inhibit Env fusogenicity and HIV-1 spread." (PMID 37459363, 2023). "How this early increase in AURKA and AURKB activity may contribute to HIV-1 infection remains to be determined." (PMID 37459363, 2023).
injury (1 paper, 2025). Damage inflicted on the body as the direct or indirect result of an external force, with or without disruption of structural continuity. "While DOXO-induced oxidative stress and NF-κB activation are well documented, our findings are the first to demonstrate that selective AURKA inhibition can simultaneously downregulate the IL-17A-driven STAT3/HIF-1α/TGF-β1/VEGF-A axis in DOXO-induced liver injury." (PMID 40872590, 2025).
ischemia (1 paper, 2023). A hypoperfusion of the BLOOD through an organ or tissue caused by a PATHOLOGIC CONSTRICTION or obstruction of its BLOOD VESSELS, or an absence of BLOOD CIRCULATION. "Our blood flow imaging analysis clearly showed that AURKA overexpression favors faster and more extensive reperfusion of the ischemia limb." (PMID 36977984, 2023). "Firstly, the samples from the dataset used to screen out the AURKA were the end phase of CLI patients; while, the sample from our experimental ischemia mouse was the acute ischemic insult." (PMID 36977984, 2023).
keloid (1 paper, 2025). An irregularly shaped, elevated mark on the skin caused by deposits of excessive amounts of collagen during wound healing. "Beyond its kinase activity, AURKA also acts as a transcription factor, underscoring its multifaceted role in keloid formation and recurrence." (PMID 41424791, 2025). "AURKA promotes keloid fibroblast proliferation and migration by forming a positive feedback loop with FOXO3a that activates AKT signaling." (PMID 41424791, 2025).
kidney cancer (1 paper, 2021). Primary or metastatic malignant neoplasm involving the kidney. "Our data suggested that the high expression level of AURKA in all types of kidney cancers might be considered as a carcinogenesis factor that could inhibit apoptosis function." (PMID 34337875, 2021).
limb ischemia (1 paper, 2023). A ischemia that involves the limb. "Aurora Kinase A (AURKA) is an essential serine/threonine kinase for mitosis, while its role in limb ischemia remains unclear." (PMID 36977984, 2023).
malignant peritoneal mesothelioma (1 paper, 2025). An aggressive malignant mesothelioma that arises from the peritoneum. "Recently, pediatric malignant peritoneal mesothelioma cases have been genetically studied, with alterations observed in ALK, EWSR1, FUS1, YY1, or in AURKA, AURKC, HLA-1B, ZNF-217, OR5F1, and MEN1 genes, but not in BAP1." (PMID 40725095, 2025).
malignant pleural mesothelioma (1 paper, 2025). A malignant neoplasm that arises from mesothelial cells in the pleura and shows a diffuse growth pattern. "In a kinome, CRISPR‐Cas9 knockout screen in which kinases in malignant pleural mesothelioma (MPM) cancer cells were targeted WEE1, AURKA, MPP3, MAP3K12, DGKD and SPEG could be identified as candidate genes." (PMID 40242936, 2025).
mantle cell lymphoma (1 paper, 2024). Mantle cell lymphoma is a rare form of malignant non-Hodgkin lymphoma affecting B lymphocytes in the lymph nodes in a region called the ``mantle zone''. "In mantle cell lymphoma and upper gastrointestinal adenocarcinomas, combining AURKA inhibitors with docetaxel has been shown to produce better treatment outcomes than using docetaxel alone." (PMID 38714583, 2024).
metastatic prostate carcinoma (1 paper, 2014). A carcinoma that arises from the prostate gland and has spread to other anatomic sites. "Amplification of AURKA has been described in treatment-resistant metastatic prostate cancer, and inhibitors of AURKA are currently in clinical trials." (PMID 25160065, 2014).
mismatch repair deficiency (1 paper, 2022). "A number of synthetically lethal therapeutic opportunities arise on the basis of ARID1A mutations and mismatch repair deficiency, utilizing inhibitors of PARP1, HDAC2/6, Aurora kinase A, CKD4/6, or PI3K/Akt." (PMID 36078038, 2022).
myelodysplastic syndrome (1 paper, 2022). A clonal hematopoietic disorder characterized by dysplasia and ineffective hematopoiesis in one or more of the hematopoietic cell lines. "Few years ago, we have demonstrated that AURKA and AURKB overexpression were associated with genomic instability in cytogenetically stratified group (Normal vs. Abnormal karyotype) of hematopoietic cells and bone marrow derived mesenchymal stem cells (MSCs) of myelodysplastic syndrome patients." (PMID 36175852, 2022).
neurofibroma (1 paper, 2013). An intraneural or extraneural neoplasm arising from nerve tissues and neural sheaths. "Genomic changes that accompany the transition of benign neurofibromas to MPNSTs occur at the HMMR/RHAMM locus, the AURKA locus and chromosome 20q (containing AURKA and TPX2)." (PMID 23328114, 2013).
non-alcoholic fatty liver disease (1 paper, 2022). "The results indicated that AURKA was mainly involved in cell cycle, DNA replication, non-alcoholic fatty liver disease, oxidative phosphorylation, proteasome, ribosome, and ribosome biogenesis in eukaryotes, RNA transport, spliceosome, and thermogenesis." (PMID 35558559, 2022).
Noonan syndrome (1 paper, 2021). Noonan Syndrome (NS) is characterized by short stature, typical facial dysmorphism and congenital heart defects. "Secondary screening confirmed the enhanced sensitivity of RIT1-mutant cells to depletion of USP9X and AURKA along with the RAS pathway and Noonan syndrome genes SHOC2 and SOS1." (PMID 34373451, 2021).
plexiform neurofibroma (1 paper, 2013). An elongated and multinodular neurofibroma, formed when the tumor involves either multiple trunks of a plexus or multiple fascicles of a large nerve, such as the sciatic. "The examination of copy number variants in human, primary dermal or plexiform neurofibromas and MPNSTs of differing grades provides an additional link between disease progression and the AURKA signalling pathway." (PMID 23328114, 2013).
rectal cancer (1 paper, 2023). A primary or metastatic malignant neoplasm that affects the rectum. "Additionally, immunohistochemistry results sourced from the THPA database supported our findings, showing elevated protein levels of AURKA in esophageal, stomach, liver, and rectal cancer tissues." (PMID 37965456, 2023).
renal tumors (1 paper, 2021). "At the onset of ccRCC and other renal tumors, mitotic Aurora kinase A (AURKA) mRNA levels are higher than in normal tissue." (PMID 33920158, 2021).
sarcopenia (1 paper, 2024). Progressive decline in muscle mass due to aging which results in decreased functional capacity of muscles. "AURKA in blood (beta: ‐0.16, 95% CI: −0.22 to −0.09, P = 2.1*10−06) and skeletal muscle (beta: 0.03, 95% CI: 0.02 to 0.05, P = 5.3*10−05) tissues showed an inverse relationship with sarcopenia risk." (PMID 38644354, 2024). "In addition, the expression of AURKA in blood and skeletal muscle tissues exhibits an inverse relationship with the risk of sarcopenia." (PMID 38644354, 2024). "Based on these integrated datasets, our study provides potential evidence for the genetic colocalization of six drug target genes (HP, HLA‐DRA, MAP 3K3, MFGE8, COL15A1, and AURKA) with sarcopenia." (PMID 38644354, 2024). "The results revealed that six potential druggable genes (HP, HLA‐DRA, MAP 3K3, MFGE8, COL15A1, and AURKA) passed the colocalization analysis and were present in more than one QTL datasets or sarcopenia‐related traits." (PMID 38644354, 2024). "However, Fostamatinib, an inhibitor of MAP 3K3 and AURKA, and coccidioides immitis spherule, an HLA‐DRA binding agent, might be not ideal drugs due to the opposite effect for sarcopenia." (PMID 38644354, 2024).
seminoma (1 paper, 2010). A radiosensitive malignant germ cell tumor found in the testis (especially undescended), and extragonadal sites (anterior mediastinum and pineal gland). "The level of AURKA differed significantly within the different histological subtypes of TGCTs (P<0.001), and was significantly higher in both seminomas and non-seminomas compared to normal testis (P=0.015 and P=0.003, respectively)." (PMID 20411023, 2010). "The expression of AURKA was significantly elevated in both non-seminomas (P=0.003) and seminomas (P=0.015)." (PMID 20411023, 2010).
serous carcinomas (1 paper, 2017). "Analyses of 223 high-grade serous carcinomas uncovered an inverse correlation between AURKA and BRCA2 protein expression, with high AURKA to BRCA2 expression ratios predicting poor survival." (PMID 28881569, 2017).
skin carcinoma (1 paper, 2012). "Using the Oncomine database, the analysis of the transcriptome of human cell lines and xenografts with sensitivity to drugs designed against AURKA, AURKB or PLK1 kinases show a profile similar to that seen in the described mouse skin carcinomas." (PMID 22880004, 2012).
steatosis (1 paper, 2019). Increased lipid within the cytoplasm of cells. "From the HE stain, we confirmed that both AURKA(WT) and AURKA(V352I) can induce steatosis in transgenic fish as early as 3 to 5 months." (PMID 31269749, 2019). "In summary, our results suggest that overexpression both AURKA(WT) and AURKA(V352I) induced expression of lipogenic factors and enzymes, indicating the AURKA(WT) and AURKA(V352I) can induce steatosis." (PMID 31269749, 2019).
tauopathy (1 paper, 2021). Neurodegenerative disorders involving deposition of abnormal tau protein isoforms (tau proteins) in neurons and glial cells in the brain. "Problem 2 asked participants to predict compounds that bind the Tauopathy pro-targets AURKA, PAK1, FGFR1, and STK11 and avoid the Tauopathy anti-targets PAK3, MAP3K7, and PIK3CA." (PMID 34520464, 2021). "Problem 2 asked participants to predict compounds that bound the Tauopathy pro-targets, AURKA, PAK1, FGFR1, and STK11 and did not bind PAK3, MAP3K7, and PIK3CA." (PMID 34520464, 2021).
testicular cancer (1 paper, 2010). A primary or metastatic malignant neoplasm that affects the testis. "AURKA expression is increased in both IGCN and TGCTs, and downregulation of the spindle checkpoint proteins together with elevated levels of AURKA in IGCN may be of importance in the transition from in situ to invasive testicular cancer." (PMID 20411023, 2010).
thymic carcinoma (1 paper, 2022). Thymic carcinoma (TC) is a type of thymic epithelial neoplasm characterized by a high malignant potential. "Meanwhile, we discovered that AURKA was significantly negatively associated with most checkpoint genes in thymic carcinoma." (PMID 36685952, 2022).
thyroid tumor (1 paper, 2015). A benign or malignant neoplasm affecting the thyroid gland. "For example, a study of 100 benign and 105 malignant thyroid tumors using a panel of 57 molecular markers found an association of tumor pathology with the expression of a subset of markers including cytokeratin 19 (CK19), LGALS3, HBME-1, VEGF, AR, p16, and AURKA." (PMID 25887408, 2015).
ulcerative colitis (1 paper, 2009). An inflammatory bowel disease involving the mucosal surface of the large intestine and rectum. "The expression of the aurora kinase A (AurkA) transcript, a regulator of mitosis that is up-regulated in patients with ulcerative colitis, was also significantly up-regulated in the long term in colon of Hnf4α mutant mice." (PMID 19898610, 2009).
urinary tract tumors (1 paper, 2025). "The AURKA expression was highly heterogeneous across urinary tract tumors, with higher expression in TGCT and lower in PRAD." (PMID 40718709, 2025).
urothelial carcinoma (1 paper, 2021). A malignant neoplasm derived from the transitional epithelium of the urinary tract (urinary bladder, ureter, urethra, or renal pelvis). "Furthermore, the SNP was a favorable prognostic factor for urothelial carcinoma patients treated with alisertib (an AURKA inhibitor)." (PMID 35201446, 2021).
Wilms tumor (1 paper, 2019). An embryonal neoplasm characterized by the presence of epithelial, mesenchymal, and blastema components. "Odds ratios (ORs) and 95% confidence intervals (CIs) were used to assess the strength of association between AURKA SNPs and Wilms tumor risk." (PMID 31636670, 2019). "In conclusion, our findings indicated that the AURKA rs8173 G>C polymorphism was associated with decreased Wilms tumor risk in Chinese children." (PMID 31636670, 2019). "We recruited 145 cases and 531 cancer-free controls to investigate whether AURKA gene variants modify Wilms tumor susceptibility." (PMID 31636670, 2019). "The role of AURKA in the development of Wilms tumor is currently lacking." (PMID 31636670, 2019).
cancer (631 papers, 2006 to 2026). A tumor composed of atypical neoplastic, often pleomorphic cells that invade other tissues. "Despite its pronounced depletion in MeT-5A cells, likely due to its inherent nature as a core essential gene, AURKA dysregulation has been implicated in a wide range of cancers with several inhibitors targeting its oncogenic activity." (PMID 40180891, 2025). "Elevated levels of AURKA are associated with aggressive cancer behaviors, including invasion, metastasis, and resistance to conventional therapies." (PMID 40564876, 2025). "On the contrary, loss of methylation of AURKA results in p21 induction and thus apoptosis of cancer cells and limited cell proliferation." (PMID 41150792, 2025). "The deregulation of AURKA has been associated with the pathogenesis of various cancers, including solid tumors and hematological malignancies." (PMID 39942770, 2025). "The Aurora kinase family, which includes AURKA, AURKB, and AURKC, has been implicated in various cancers, with overexpression linked to chromosomal amplification of the AURKA gene." (PMID 40564876, 2025). "Dysregulated expression or activity of AURKA is strongly associated with the development of various cancers." (PMID 40746357, 2025). "Recent advances have identified promising biomarkers, such as CNIH4, linked to cancer stemness and immune modulation, and AURKA, associated with cuproptosis and ferroptosis, both implicated in HNC progression." (PMID 40087718, 2025). "Prognostic evaluation using Cox regression modeling revealed significant associations between AURKA expression levels and overall survival in 16 cancer types." (PMID 41357242, 2025). "The results of GSVA and GSEA demonstrated that majority of cancer hallmark signatures were significantly enriched in high AURKA HCC, such as PI3K–AKT–MTOR signaling (a classical downstream cascade of AURKA)." (PMID 40311679, 2025). "Aurora A, encoded by the AURKA gene, is a well‐established oncogenic protein implicated in various cancers, including ESCC." (PMID 40702875, 2025). "This compound is used in anti-cancer therapy to inhibit AURKA, which is involved in mitotic spindle formation and organization, and has been implicated in DNA signaling in cancers." (PMID 41004518, 2025). "While AURKA amplification is the critical initiating upstream event in causing cancer, increased transcription or stabilization of AURKA protein in many cancers can also lead to its upregulation and activation." (PMID 39334449, 2024). "Aurora kinase A, also known as serine/threonine-protein kinase 6, encoded by gene AURKA, a crucial regulator of the cell cycle, plays a significant role in cancer progression." (PMID 38995006, 2024). "This indicates that the Asp132-mutation of AURKA did decrease the sensitivity of cancer cells to Taxol in vitro." (PMID 38994036, 2024). "A prominent association exists between high expression of AURKA and cancer, and impairment of AURKA levels can trigger its oncogenic activity." (PMID 39527514, 2024). "Given its involvement in cancer, high levels of AURKA have been linked to clinical aggressiveness, poor outcomes, unfavourable prognoses, therapeutic resistance, and increased early recurrence in HCC patients." (PMID 38590119, 2024). "Among these genes, the increased expression of aurora kinase A (AURKA) has been implicated in various cancers." (PMID 38673957, 2024). "Various single nucleotide polymorphisms (SNPs) of the AURKA gene have also been associated with cancer development and susceptibility." (PMID 39527514, 2024). "Our review examines the most recent advances in AURKA regulation and focuses on 33 such direct cancer-specific targets of AURKA and their associated oncogenic signaling cascades." (PMID 39334449, 2024).